RN7SL319P (RNA, 7SL, cytoplasmic 319, pseudogene)
Gene: Miscellaneous RNA gene on chromosome 15 (75,785,134 to 75,785,354, forward strand). Ensembl gene ENSG00000241807.
Homologues: Orthologues: chimpanzee Metazoa_SRP (95% identical), macaque Metazoa_SRP (74% identical), pig Metazoa_SRP (63% identical). Paralogues in human: RN7SL214P (93% identical), RN7SL241P (90% identical), RN7SL536P (89% identical), Metazoa_SRP (88% identical), RN7SL106P (88% identical), RN7SL238P (88% identical), RN7SL545P (88% identical), RN7SL759P (88% identical), RN7SL469P (87% identical), RN7SL673P (87% identical), RN7SL495P (86% identical), RN7SL628P (86% identical), and 709 more.